GSDME (gasdermin E)
Diseases named in the same sentence as GSDME in open-access papers (continued):
Sharing a sentence is not in itself a finding about the gene and the disease.
tumor (continued). "In current study, we found that most PRGs are differentially expressed in BC, suggesting the potential role in tumorigenesis, which was consistent with the research by Zhang, that GSDME, functioning as a tumor suppressor, suppressed tumor progression via inducing pyroptosis." (PMID 35464869, 2022). "Although current studies focused on the field of tumor therapy, while GSDME could also trigger cytokine storms by forming inflammatory responses, and a large amount of GSDME expression has been observed in the damaged hippocampus." (PMID 35782390, 2022). "Furthermore, the pyroptosis-inducing activity and tunability of this nanotuner displayed a positive correlation with the GSDME expression of tumor cells, and upregulation of GSDME expression by demethylation further facilitated the ANPS-mediated pyroptosis." (PMID 39872743, 2022). "Therefore, in our study, we found that GSDME was differentially expressed in human RB tissues and that GSDME expression was inversely proportional to tumor stage." (PMID 35480866, 2022). "Using AsPC-1 cells in which GSDME was knocked out, we further demonstrated that only WT GSDME (not GSDME-D270A or WT GSDMB) rescued the GSDME-deficiency-retarded tumour growth in the pancreas." (PMID 35292781, 2022). "Recent studies indicated that the pyroptosis-related gene (GSDME) could suppress tumor growth by activating anti-tumor immunity." (PMID 35741587, 2022). "First, GSDME is hardly expressed in most tumor cells, but abundantly expressed in normal cells." (PMID 36209102, 2022). "Therefore, the clinical use of a specific inhibitor of gasdermin D for the activation of gasdermin E in tumor cells, and the blocking of gasdermin D, can prevent the occurrence of CRS while exerting CAR-T efficacy, thus improving the safety of treatment." (PMID 36038533, 2022). "GSDME was shown to be sensitive to a number of anti-neoplastic drugs among others, which is reported to be suppressed via epigenetic inactivation in various cancers and considered as a tumor suppressor gene." (PMID 36605187, 2022). "However, scientists also pointed out that because of methylation, GSDME is under-expressed in most tumor cell lines, while it is generally over-expressed in normal cell lines." (PMID 36497244, 2022). "Lobaplatin, an anti-tumor drug, has been shown to induce GSDME-dependent pyroptosis." (PMID 36077828, 2022). "Moreover, granzyme B (GZMB) released from T cells can cleave GSDME directly or through Caspase-3 in target cells and activate extensive pyroptosis, further promoting antitumor immune response and inhibiting tumor growth." (PMID 35990696, 2022). "Based on accumulating evidence, GSDME functions as a tumour suppressor in many cancers." (PMID 35896522, 2022). "However, chemotherapy resistance exists because GSDME expression levels are low in most tumor cell lines, owing to GSDME promoter methylation." (PMID 35990696, 2022). "The mechanism underlying these effects was further investigated, and the findings indicated that GA can inhibit CRC cells in vitro and in vivo by triggering caspase-3/GSDME-dependent pyroptosis, which further triggers an antitumor immune response that inhibits tumor growth." (PMID 36428598, 2022). "Decitabine can promote the expression of GSDME and induce pyroptosis of tumor cells." (PMID 35883480, 2022). "Both cell types can also release granzyme B to activate GSDME-mediated pyroptosis in tumor cells." (PMID 36077828, 2022). "In the treatment of tumor patients, chemotherapeutic resistance of tumor cells is an inevitable problem that contributed to high mortality, and GSDME might play an important role in the generation of resistance to chemotherapy in cancer cells." (PMID 35462927, 2022). "Importantly, different studies have described that conventional chemotherapy threatening off-target toxicities are induced by the activation of GSDME mediated pyroptosis in non-tumor cells, as these agents lack tumor targeting capacity." (PMID 35120582, 2022).
tumor (continued). "Indeed, it is demonstrated that chemotherapeutic drugs induce caspase-3-mediated gasdermin E (GSDME) cleavage, leading to the formation of N-GSDME and tumor cells pyroptosis." (PMID 35682876, 2022). "Consistent with previous in vitro experiments, Ad-vp3 and Ad-vt treatment increased the levels of cleaved-PARP, cleaved-GSDME, cleaved-caspase-3, cleaved-caspase-9, and up-regulated the expression of bax and cytochrome C. In summary, apoptin can inhibit tumor growth and induce pyroptosis in vivo." (PMID 35002520, 2022). "For example, the classic anti-tumor drugs cisplatin and paclitaxel, in addition to inducing tumor cell apoptosis, have also been found to participate in the anti-tumor mechanism by inducing pyroptosis through the GSDME pathway." (PMID 36248872, 2022). "Additionally, GSDME, which is regarded as a potential tumor suppressor, is confirmed to execute pyroptosis after the cleavage of caspase-3." (PMID 35819638, 2022). "The expression of DFNA5 (nonsyndromic hearing impairment protein 5)/GSDME was lower in most tumor cells than in normal cells due to hypermethylation and DNA methylase inhibitor 5-aza-20-deoxycytosine (decitabine) could derepress GSDME in vitro." (PMID 36177050, 2022). "In order to determine whether the mechanism of tumor volume reduction we observed in vitro was casp-3/GSDME-mediated pyroptosis, we extracted proteins from the tumors and performed Western blot experiments." (PMID 36551691, 2022). "In addition, during the tumor microenvironment estimation, we found that expression of GSDME was positively correlated with StromalScore in CRC(r = 0.84)." (PMID 35164740, 2022). "The expression level of GSDME in tumor and adjacent normal tissue was significantly different." (PMID 35922531, 2022). "GSDME exerts its tumor suppressor effect in three main aspects." (PMID 35462927, 2022). "Most tumor cells inhibit GSDME via methylation modification with a DNA methyltransferase inhibitor." (PMID 35883480, 2022). "GSDME deficiency did not affect subcutaneous tumour growth, whereas orthotopic tumour growth was markedly inhibited in the pancreas." (PMID 35292781, 2022). "Recently, researchers found that GSDME-mediated pyroptosis can release various inflammatory factors and DAMPs, and stimulate a strong inflammatory response to regulate the tumor immune microenvironment, resulting in the activation of an antitumor immune response." (PMID 36612023, 2022). "Cisplatin induces a higher rate of GSDME-mediated pyroptosis than paclitaxel in A549 cells, suggesting that cisplatin may be more effective at killing tumours with high levels of GSDME." (PMID 35896522, 2022). "In addition, although GSDME−/− tumour cells lost the resistance to digestive enzymes, re-expression of exogenous MUC1 or MUC13 largely restored their resistance, and the co-expression of MUC1 and MUC13 achieved the greatest resistance." (PMID 35292781, 2022). "In this study, we further demonstrated that PDAC tumour cells express GSDME at high levels." (PMID 35292781, 2022). "In addition, the abnormal expression of GSDME was significantly related to the tumor stage and grade in ccRCC." (PMID 35321945, 2022). "We hypothesized that ROS levels increase in circulating tumor cells at the early stage of tumor cell entry into the liver and induce slight caspase-3 activation, which cleaves GSDME proteins to punch holes in the tumor cell membrane." (PMID 36438480, 2022). "Importantly, GSDME is emerging as an important tumor suppressor gene and a valuable molecular marker of human cancers, since GSDME regulated pyroptosis conduces to the cytotoxicity of various chemotherapeutic agents." (PMID 36189207, 2022). "The anti-tumor activity may be achieved by regulating the intestinal microbiota, improving the function of the intestinal barrier, and inhibiting GSDME mediated pyroptosis." (PMID 35910578, 2022).
tumor (continued). "However, in some tumor cell lines, the expression level of GSDME was lower than that in normal cell lines, leading to the accidental injury of normal tissues during chemotherapy." (PMID 36482419, 2022). "Once cleaved, GSDMB and GSDME induce pyroptosis in tumor cells." (PMID 36159393, 2022). "However, GSDME was often silenced in tumor tissues with promoter methylation, thus avoiding the occurrence of chemotherapeutic drug-induced pyroptosis and resisting antitumor effects." (PMID 35847844, 2022). "The expression of GSDME is inhibited in most cancer tissues and as such, GSDME may act a tumor suppressor." (PMID 34553845, 2022). "However, another study demonstrates that GSDME acts as a tumor suppressor by activating pyroptosis, enhancing antitumor immunity." (PMID 35443644, 2022). "Tumor‐cell‐derived microvesicles whose plasma membranes are infused with methotrexate could induce pyroptosis in CCA cells through a GSDME‐dependent pathway." (PMID 34459122, 2021). "GSDME has been also reported to induce anti-tumor immunity with killer lymphocytes and TAMs 47, which might also facilitate M1 phenotype Mφ during crosstalk." (PMID 33859743, 2021). "Of note, cleaved GSDME played a key role in strengthening tumor immunosuppression." (PMID 33634141, 2021). "The expression of caspase-4 and GSDME was significantly inhibited in the tumor tissues." (PMID 34659633, 2021). "Here, we suggest that GSDME acts as a tumor suppressor because of its multiple functions in cell death modulation by inducing pyroptosis, potentiating caspase-3 cleavage with mitochondrial apoptotic pathway activation, and elevating extrinsic death protein expression." (PMID 34490348, 2021). "Based on the given evidence, GSDME function as a tumor suppressor." (PMID 33634141, 2021). "In addition, GSDME expression enhances anti-tumor adaptive immunity by promoting macrophage-mediated phagocytosis, which prevents immune evasion of tumor." (PMID 33941231, 2021). "BRAFi + MEKi treatment could promote cleavage of GSDME to regulate the tumor immune microenvironment." (PMID 34459122, 2021). "Several studies have shown the definite role of GSDME in tumor growth and chemotherapy resistance." (PMID 33542198, 2021). "In addition to caspase-3, GzmB also cleaves GSDME protein at D270 to initiate pyroptosis in GSDME-expressing tumor cells." (PMID 33941231, 2021). "On one hand, GSDME is low expression in most cancers and decreased GSDME levels are also related to reduced survival prognosis, indicating that GSDME might function as a role of tumor suppressor." (PMID 34381728, 2021). "Activated caspase-1 and caspase-11/4/5 cleave gasdermin D (GSDMD) in inflammatory cells, while caspase-3 cleaves gasdermin E (GSDME) in tumor cells, to release the N terminal domain of gasdermins that inserts into the plasma membrane to form pores that allow intracellular molecules to pass through." (PMID 33430381, 2021). "This may, in part, explain the decreased survival of patients harboring a low GSDME expression in their tumor, which might be more resistant to pyroptotic cell death, and to secondary amplification and protection by the immune responses." (PMID 34490126, 2021). "Although previous studies have mainly focused on the anti-tumor effect of tetraarsenic hexoxide on apoptosis, we first found that tetraarsenic hexoxide markedly induced pyroptotic cell death through caspase-3-mediated cleavage of GSDME in TNBC cells." (PMID 33558527, 2021). "Uncleavable or pore-defective GSDME proteins are also not tumour suppressive and many cancer-associated GSDME mutations reduce GSDME function, suggesting that GSDME inactivation is a strategy developed by cancer cells to reach the immune evasion." (PMID 33602906, 2021).
tumor (continued). "In agreements, GSDME expression is inactivated in most tumor cells through two complementary mechanisms: downregulation of expression based on epigenic hypermethylation of the promoter, or loss-of-function mutations resulting in an inactive protein unable to form a membrane pore." (PMID 34490126, 2021). "Activated GSDMD/GSDME protein leads to the formation of membrane pores and mediates the maturation and release of IL-1β and IL-18, which subsequently induces strong inflammatory response in tumor microenvironment." (PMID 34830775, 2021). "Recent studies have shown that the gene GSDME is a tumor suppressor that can enhance the phagocytosis of tumor-associated macrophages and promote the infiltration and activation of NK cells and CD8+ T lymphocytes, thereby inhibiting tumor growth." (PMID 34837692, 2021). "Recent studies have indicated that GSDME induces tumor cell death by inducing apoptosis and pyroptosis, which may explain its potential tumor suppressive activity." (PMID 34858408, 2021). "Thus, it will be beneficial to target GSDME or to elevate tumor-derived GSDME expression level in cancer treatment." (PMID 34421915, 2021). "Combining decitabine (DAC) with chemotherapy nanodrugs to manage drugs to activate and upregulate the caspase‐3/GSDME signal, further triggers pyroptosis in tumor cells, therefore strengthening the immunological effect of chemotherapy with cisplatin in a mouse triple‐negative breast cancer model." (PMID 34459122, 2021). "Meanwhile, GSDME expression silencing in multiple cancer cells via DNA methylation of the promoter region related it to tumor metastasis and chemotherapy resistance, indicating its role as a tumor suppressor." (PMID 33542198, 2021). "Our group found that the natural product triptolide exerts tumor suppression activity through inducing GSDME-mediated pyroptosis in head and neck cancer cells (unpublished data), highlighting its potential to serve as an adjuvant approach for cancer immune therapy." (PMID 33941231, 2021). "GSDME contributes to tumor suppression by activating antitumor immunity." (PMID 33634141, 2021). "In addition, GSDME can be cleaved by caspase-3, an acknowledged apoptotic caspase, in GSDME-expressing tumor cells and GSDME-negative cells with extrinsic overexpressed GSDME to induce pyroptosis." (PMID 33542198, 2021). "Studies have showed that GSDME-knockout in tumor cells could eliminate CRS, which provided a new reference for reducing CRS after using CAR-T therapy clinically." (PMID 34381721, 2021). "In most cancers, GSDME expression is decreased in tumor tissues compared to normal tissues." (PMID 34298833, 2021). "Moreover, caspase-3 cleavage of GSDME in chemotherapy mediates anti-tumor immunity, substantiating GSDME’s role as a tumor suppressor gene." (PMID 34490348, 2021). "Therefore, GSDME plays dual tumor-suppressive roles and lies in the intersection between pyroptotic cell death and rejuvenation of immune microenvironment, offering the possibility of harnessing its function to treat cancer." (PMID 34901025, 2021). "GSDME-knockout mice subjected to chemotherapy also showed reduced tissue damage compared with WT mice subjected to the same treatment, suggesting an extra role of GSDME in addition to tumor suppression." (PMID 33542198, 2021). "Upregulation of GSDME had no remarkable impact on tumor growth in killer lymphocyte-depleted or PFN-deficient mice." (PMID 33634141, 2021). "In another study conducted by the same authors, GSDME methylation resulted in lower expression of its protein in breast cancer cells compared to normal cells, and in the inability to activate pyroptosis in tumor cells." (PMID 33840390, 2021). "GSDME may be a tumor suppressor, as its expression is decreased in breast, gastric, and colorectal cancers." (PMID 34858408, 2021).
tumor (continued). "Considering that pyroptosis represented a form of proinflammatory cell death, it was plausible to speculate that tumor immune milieu might be broadly altered by GSDME upregulation in transformed mesenchymal cells as compared to the epithelial counterparts." (PMID 34901025, 2021). "Thus, it has been suggested that supplementation of iron can maximize the anti-tumor effect of drugs that induce ROS to inhibit growth of melanoma tumor via GSDME-dependent pyroptosis." (PMID 32340261, 2020). "BIX may change the state of GSDME methylation dependent inhibiting G9a, which sensitizes the tumor to chemotherapy." (PMID 32437063, 2020). "GSDME is highly expressed in normal tissues, and is known to be a candidate tumor suppressor." (PMID 33133646, 2020). "Some scholars have suggested that during the treatment of malignant tumors, appropriate chemotherapeutic drugs can be selected according to the expression of GSDME, thereby increasing the sensitivity to chemotherapeutic drugs, enhancing the anti-tumor immunity and reducing drug resistance." (PMID 33133646, 2020). "Furthermore, in tumor cells with low GSDME expression, the DNA methyltransferase inhibitor Decitabine, can inhibit the hypermethylation of its promoter to increase the expression of GSDME in tumor cells and induce pyroptosis." (PMID 33133646, 2020). "Although pyroptosis enhanced drug sensitivity, reduced the anti-apoptotic properties of tumors, and enhanced the anti-tumor immunity, high expression of GSDME could also increase the side effects of chemotherapy." (PMID 33133646, 2020). "When the expression of GSDME was low in tumor cells, the DNA methyltransferase inhibitor Decitabine could inhibit the hypermethylation of its promoter, thus further promoting the pyroptosis of tumor cells." (PMID 33133646, 2020). "Although the expression level of GSDME is suppressed with the potential as a tumour suppressor, it is still unclear whether and how GSDME acts as a tumour suppressor." (PMID 32404864, 2020). "Due to the heterogeneity of tumor cells, the high expression of GSDME may hint that GSDME probably exerts an alternative function in tumor cells." (PMID 32437063, 2020). "However, GSDME is mainly highly expressed in normal cells, and is low in tumor cells due to the hypermethylation of its promoter." (PMID 33133646, 2020). "Therefore, scientifically-sound studies are still needed to explore the expression partner of GSDME in various type of tumours." (PMID 30804337, 2019). "We hypothesize that GSDME plays a role in creating a more inflammatory microenvironment around the tumor, by induction of necrosis or pyroptosis." (PMID 31434357, 2019). "Due to the recent progress in unravelling the function of gasdermins, we speculate that GSDME may have a more subtle effect in tumor biology by creating a more inflammatory microenvironment." (PMID 31434357, 2019). "In tumor cell lines with low-level GSDME, the expression of GSDME was upregulated in the corresponding cell lines after treatment with the distamine, and the sensitivity of tumor cells to chemotherapy drugs was also increased, which made these cells more prone to pyroptosis." (PMID 31501419, 2019). "Furthermore, flow cytometry analyses showed that GSDME-knockout tumour tissues had a higher percentage of annexin V single-positive cells and fewer annexin V and 7-AAD double-positive cells." (PMID 30804337, 2019). "Apart from its involvement in HL, GSDME functions as a tumor suppressor." (PMID 31637008, 2019). "Indeed, our findings show that GSDME expression suppresses tumor cell growth in vitro and delays tumor formation and growth in vivo." (PMID 30976076, 2019). "Studies have shown that DFNA5 (nonsyndromic hearing impairment protein 5)/GSDME (Gasdermin-E) mRNA methylation results in lower expression levels of DFNA5/GSDME in most tumor cells than in normal cells, making it difficult to activate the pyroptosis in most tumor cells." (PMID 31501419, 2019).